CDK4 (cyclin dependent kinase 4)
Diseases named in the same sentence as CDK4 in open-access papers (continued):
Sharing a sentence is not in itself a finding about the gene and the disease.
breast cancer (continued). "Disappointedly, our ChIP assay showed that the ER did not interact with the CDK2 or CDK4 promoter regions, suggesting that BC-N102 downregulates the expression of CDK2 and CDK4 independent of the ER in breast cancer cell lines." (PMID 34421361, 2021). "Overexpression of p16-mediated resistance to CDK4/6 inhibitors in the absence of Rb and low expression of p16 did not rescue the clinical benefit in Rb-positive luminal breast cancer patients in the phase II palbociclib monotherapy trial." (PMID 33364954, 2020). "Moreover, we found a strong positive correlation between the expression of p-RB (an indicator of CDK4/6 activity), p-USP51 and ZEB1 in metastatic human breast cancer samples." (PMID 32296027, 2020). "Among these markers, the role of cyclin D1 and p16 expression as prognostic markers for CDK4/6 inhibitors is still controversial, even in similar groups of patients with ER+/HER2- breast cancer, and requires further evaluation in preclinical and clinical models." (PMID 32899250, 2020). "Anticancer drugs are specifically designed to inhibit cell growth, thus we evaluated cytotoxic efficacy of the antimetabolites pemetrexed and fluorouracil in combination with the CDK4/6 inhibitor palbociblib in the TZM-bl cell line and in two distinct breast cancer cell lines, MDA-MB-468 and T47D." (PMID 32197329, 2020). "Several cyclin-dependent kinase 4/6 (CDK4/6) inhibitors are indicated in the treatment of metastatic hormone receptor-positive (HR)/ human epidermal growth factor receptor 2 (HER2) negative breast cancer which includes palbociclib, ribociclib and abemaciclib." (PMID 32985794, 2020). "This review aims to summarize the current knowledge on drugs used in adjuvant, neoadjuvant and palliative chemotherapy, hormone therapy, anti-HER2 drugs, CDK4/6 inhibitors, PARP (poly ADP-ribose polymerase) inhibitors, and immune therapy in breast cancer patients undergoing HD and PD." (PMID 32508921, 2020). "As CDK4/6 inhibitors including ribociclib, abemaciclib, and palbociclib start to occupy a key role in the treatment of HR+, HER2− breast cancer, our interest focused on creating a ribociclib-resistant cell line from the widely used and characterized ER+, HER2− CAMA-1 cell line." (PMID 32565737, 2020). "The development of inhibitors of CDK4 and CDK6 has changed the perception of CDKs as therapeutic targets in breast cancer following “underwhelming results and unacceptable toxicity were seen with pan-CDK inhibitors such as flavopiridol (alvocidib) in the early 2000s”." (PMID 32351542, 2020). "CDK4/6, which phosphorylates Rb to drive cell cycle progression and is a therapeutic target in breast cancer and other malignancies, is not upregulated in SCLC." (PMID 32224870, 2020). "Even though the mechanism is not very clear, HDAC inhibition works synergistically with CDK4/6 inhibitors in luminal breast cancer." (PMID 33364954, 2020). "CDK4/6 inhibitors with either aromatase inhibitors or antiestrogens are currently recommended as first-line treatment option for metastatic ER-positive and HER2-negative breast cancers." (PMID 32979150, 2020). "Dysregulation of the cell cycle is a hallmark of cancer that leads to aberrant cellular proliferation and inhibition of cell cycle regulators such as Cyclin-Dependent Kinase 4 (CDK4) and 6 (CDK6) has become a new therapeutic target for the treatment of breast cancer." (PMID 31936350, 2020). "Finally, our data also support the evaluation of upfront triple PI3K:CDK4/6:ER combination therapy to delay and/or prevent the acquisition of therapeutic resistance in ER+/HER2− breast cancer." (PMID 32795346, 2020). "Several clinical studies that were carried out during the last years led to the approval by the Federal Drug Administration and European Medicines Agency of three selective CDK4/6 inhibitors, Palbociclib, Ribociclib and Abemaciclib, for the treatment of advanced metastatic HR+/HER2- breast cancer." (PMID 32210163, 2020).
breast cancer (continued). "For instance, mice lacking cyclin D1 or CDK4, as well as mice expressing mutant cyclin D1 (incapable of activating CDK4/6) were resistant to breast cancer induced by the Erbb2/HER2 oncogene." (PMID 30959874, 2019). "Recently, CDK4/6 inhibitors have demonstrated a progression free survival (PFS) and overall survival benefit when combined with standard endocrine therapy in advanced hormone receptor (HR)+/HER2- breast cancer." (PMID 31695840, 2019). "Also in the breast cancer field, in a phase III clinical trial of breast cancer treatment with CDK4/6 inhibitors, the detection of changes in ctDNA PIK3CA levels after 15 days of treatment predicts progression-free survival (PFS) after treatment." (PMID 30849971, 2019). "The prevalence of HER2 mutations appears to be considerably higher in these patients, who received endocrine therapies with or without CDK4/6 inhibitors, compared with the HER2 mutation frequency established in untreated primary breast cancer." (PMID 31341951, 2019). "Perhaps, the prediction of the CDK4/6 inhibitor sensitivity could determine the levels of CDK4 and CDK6 in breast cancer." (PMID 31448056, 2019). "In addition to breast cancer, the synergistic anti-tumor effect of dual inhibition of the PI3K/AKT/mTOR pathway and CDK4/6 has also been demonstrated in malignant pleural mesothelioma, T-cell acute lymphoblastic leukemia, and mantle cell lymphomas." (PMID 31101835, 2019). "Three selective CDK4/6 inhibitors (palbociclib, abemabiclib, ribociclib) are currently FDA-approved based on their proven ability to increase progression-free survival in ER+ breast cancer patients." (PMID 31100952, 2019). "The combination of palbociclib, a selective inhibitor of the cyclin-dependent kinases CDK4 and CDK6, and ovarian suppression with letrozole significantly prolonged progression-free survival in women with ER+/HER2– advanced breast cancer in the PALOMA-3 (NCT01942135) study." (PMID 32039034, 2019). "Importantly, palbociclib, a small‐molecule inhibitor of CDK4 and CDK6, combined with letrozole has recently been approved to treat postmenopausal women with ER‐positive, HER2‐negative advanced breast cancer as a first‐line therapy." (PMID 30714150, 2019). "Although these studies suggested the use of CDK4/6 inhibitors in HER2-positive breast cancer, they did not investigate mechanisms of resistance to HER2-targeted approaches." (PMID 30959874, 2019). "Thus, we propose breast cancers with FGFR pathway alterations should be considered for trials using combinations of ER, CDK4/6 and FGFR antagonists." (PMID 30914635, 2019). "Additionally, TiHo-0906 cells at low and high passage also displayed CNGs in regions harbouring other known breast cancer-related genes like FOXO3 and MYB (FCA B2), AKT1 (FCA B3), and GATA-3, CCND2, CDK4 and PFDN5 (FCA B4)." (PMID 30185896, 2018). "In February 2015, the CDK4/6 inhibitor, palbociclib, in combination with letrozole, was approved by the FDA as first-line treatment of metastatic postmenopausal, hormone receptor (HR)-positive breast cancer." (PMID 29218462, 2018). "The CDK4/6 inhibitor of CDK4 (INK4)-retinoblastoma (Rb) pathway plays a crucial role in cell cycle progression, and its dysregulation is an important contributor to endocrine therapy resistance in breast cancer." (PMID 30308939, 2018). "CDK4/6 inhibition substantially improves progression-free survival (PFS) for women with advanced estrogen receptor-positive breast cancer, although there are no predictive biomarkers." (PMID 29497091, 2018). "CDK4/6 inhibitors have substantial efficacy in the treatment of advanced estrogen (ER) receptor-positive HER2-negative breast cancer, the most common subtype of breast cancer." (PMID 29497091, 2018).
breast cancer (continued). "The positive results from PALOMA-2 and MONALEESA-2 indicate that the combination of letrozole and a CDK4/6 inhibitor is likely to become a major treatment option for first-line therapy of advanced, ER-positive, HER2-negative breast cancer in postmenopausal women." (PMID 30564467, 2018). "Cell lines in which CDK4 knockdown but not CDK6 knockdown had a pronounced effect on growth were enriched for those derived from breast cancers." (PMID 30443290, 2018). "Further research is required to determine the optimal treatment sequence for CDK4/6 inhibitors in advanced HR+, HER2− breast cancer, particularly since current data in the second-line setting are from patients who have received no prior CDK4/6 inhibitor-based therapy." (PMID 29164421, 2018). "Besides, CDK4/6-mediated activation of DUB3 has been reported to be essential to deubiquitinate and stabilize SNAIL1, a key factor promoting EMT and involved in breast cancer metastasis." (PMID 29789536, 2018). "Currently, estrogen receptor-positive, human epidermal growth factor receptor 2 (HER2)-negative status in breast cancer patients is the only used predictive biomarker for response to CDK4/6 inhibition." (PMID 29541385, 2018). "In conclusion, triple combination targeting therapy (HER2 and CDK4/6 inhibitors combined with antihormonal therapy) remains promising in HR+/HER2+ breast cancer, given largely nonoverlapping resistance mechanisms to the agents in this combination." (PMID 30018827, 2018). "Expression of cyclin-dependent kinase 4/6 (CDK4/6) may be increased in metastatic cancer, for example, breast carcinoma metastatic to the brain, and thus the gene is a therapeutic target." (PMID 30135398, 2018). "Overall, our study demonstrates that the CDK4/6–DUB3 axis functions as an important regulatory mechanism of breast cancer metastasis and provides a potential therapeutic approach in the management of breast cancer metastasis." (PMID 28067227, 2017). "Overall, our study establishes the CDK4/6–DUB3 axis as an important regulatory mechanism of breast cancer metastasis and provides a rationale for potential therapeutic interventions in the treatment of breast cancer metastasis." (PMID 28067227, 2017). "In year 2013, FDA approved CDK4 and CDK6 inhibitors for breast cancer as breakthrough therapies." (PMID 28241745, 2017). "Loss of CDK4/6 cell cycle regulation occurs in 20–35% of breast cancer and promotes CDK2 activity, driving the cell cycle progression without the need of CDK4/6." (PMID 27923036, 2017). "Overall these data indicate that abemaciclib is a CDK4 and CDK6 inhibitor that, as a single agent, blocks breast cancer cell progression, and upon longer treatment can lead to sustained antitumor effects through the induction of senescence, apoptosis, and alteration of cellular metabolism." (PMID 29050219, 2017). "Mechanistically, we identify a deubiquitinase, DUB3, as a target of CDK4/6; CDK4/6-mediated activation of DUB3 is essential to deubiquitinate and stabilize SNAIL1, a key factor promoting epithelial–mesenchymal transition and breast cancer metastasis." (PMID 28067227, 2017). "Being the most frequently amplified gene in human cancers, and because of its role in promoting normal stem cell expansion and mammary progenitors, CDK4 may represent a key regulator of BCSC stemness, tumor relapse and drug resistance in breast cancer." (PMID 27759034, 2016). "Together, these results strongly suggest that blocking CDK4 activity leads to increased expression of the differentiation factor BMP4, resulting in decreased CD44+/CD24− BCSC numbers, and further leading to inhibition of breast cancer stemness." (PMID 27759034, 2016). "Our data also rule out CDK6 in the maintenance of breast cancer stemness and indicate that CDK4 is the predominant regulator of cancer stemness, thereby representing a unique and specific prognostic marker for basal-like TNBC patients." (PMID 27759034, 2016).
breast cancer (continued). "No drugs targeting CDKN2A/B have been approved, while CDK4/6 inhibitor paboxilin has been proved in breast cancer by FDA." (PMID 27974690, 2016). "Palbociclib is a CDK4/6 inhibitor that received FDA approval for treatment of hormone receptor positive (HR+) HER2 negative (HER2neg) advanced breast cancer." (PMID 27634906, 2016). "CDK4 amplification has been observed in several malignancies including glioma, breast cancer, and lung cancer, and an absence of CDK4 amplification in WD and DD liposarcomas is associated with lower rate of recurrence and favorable prognosis." (PMID 26840018, 2016). "NEK2A expression is regulated by CDK4, which is a major regulator of CA in Her2+ breast cancer cells, suggesting that NEK2A may be a downstream target of CDK4, and is involved in CDK4 induced CA." (PMID 25705694, 2015). "Interestingly, in mouse models the kinase activities of some cyclin/CDK complexes, such as CDK4 and CDK2, appear dispensable for normal mouse development, but are required for mammary tumor development." (PMID 25914884, 2015). "Indeed, there are emerging reports suggesting that synergy can be achieved with the combination of CDK4/6 inhibitors and PI3K inhibitors in breast cancer or with insulin-like growth factor receptor 1 (IGF1R) inhibitors in pancreatic cancer." (PMID 26337082, 2015). "It is noteworthy that an inhibitor of the essential non-mutated cell cycle regulatory enzymes, CDK4 and CDK6, palbociclib, was recently found to double the progression-free survival of breast cancer patients without causing excessive toxicity." (PMID 26221874, 2015). "The zinc finger-homeodomain transcription factor, δ-crystallin enhancer factor 1 (δEF1) has been identified as a regulatory factor involved in the promotion of breast cancer cell proliferation via the downregulation of p21 and the upregulation of cyclin-dependent kinase-2 (CDK2) and CDK4 expression." (PMID 24348783, 2014). "However, across all 48performing screens, CDK4 and FOXA1 each show BF > 20 in 4 cell lines; two of the four CDK4lines and three of the four FOXA1 lines are HER2+ breast cancer lines, and theremainder are all luminal subtype." (PMID 24987113, 2014). "The function of cyclin D1 in mammary oncogenesis in mice is mediated through the activation of its regulatory partner CDK4, as mice lacking CDK4 or expressing the CDK4/CDK6-specific inhibitor INK4A are resistant to HER2-induced mammary tumor formation." (PMID 23786849, 2013). "This is consistent with our previous observations that in MCF10A cells expressing control pLKO.1, H-RasG12V, H-RasG12V&c-Myc, or in HER2+ breast cancer cells, knockdown of CDK4 does not greatly influence DNA replication or cell cycle progression." (PMID 23886499, 2013). "In addition to CCND1/CDK4 complexes, over-expression of CCND1 also leads to accumulation of activated CCND1/CDK2 complexes in breast cancer cells." (PMID 23390492, 2013). "To assess whether silencing of CDK4 altered radioresistance in other breast cancer subtypes, we generated HCC1954 and SKBR3 cells (both ER-PR-HER2+ cell lines) knocked down for CDK4." (PMID 23886499, 2013). "Next, we targeted both Cdk2 and Cdk4 in non-tumorigenic and Her2+ breast cancer cells using independent siRNA duplexes." (PMID 23776583, 2013). "The treatment of HER-2/neu-overexpressing breast cancer cells with AC downregulated Cdk4 without altering the Cdk1/2 protein." (PMID 22701509, 2012). "miR-195 was shown to inhibit cyclin D1 in HCC and breast cancer, CCND3 in glioblastoma, CDK4 in bladder cancer, CDK6 in HCC, E2F3 in HCC and glioblastoma, BCL-2 in breast and colorectal cancer, RAF1 in breast cancer, and GLUT3 in bladder cancer." (PMID 23335942, 2012). "Molecular profiling of the JIMT-1 human breast cancer cell line derived from a woman with progressive HER2-amplified disease while receiving trastuzumab did identify a small amplicon on 12q14.1, which contains the CDK4 gene." (PMID 19874578, 2009).
breast cancer (continued). "Given the data from the current study as well as published work, there is a strong rationale for clinical development of PD 0332991 focusing on ER-positive luminal breast cancer as well as HER2-amplified disease and combining CDK4/6 inhibition with anti-estrogen or anti-HER2 therapy, respectively." (PMID 19874578, 2009). "Although additional tissue specific roles for cdk4 have been suggested, they do not appear to be required in this breast cancer cell culture model." (PMID 18060053, 2007). "Palbociclib, ribociclib, and abemaciclib are among the Cyclin-dependent kinase 4 and 6 (CDK4/6) inhibitors that have become an innovative family of targeted therapy for hormone receptor-positive, Human Epidermal Growth factor receptor 2 (HR+/HER2-) breast cancer." (PMID 41930171, 2026). "In breast cancer, the addition of fulvestrant to alisertib failed to improve response rates or progression-free survival; however, alisertib monotherapy showed therapeutic potential in endocrine- and CDK4/6 inhibitor–resistant settings." (PMID 41562677, 2026). "Although recent literature and clinical guidelines increasingly support the use of CDK4/6i in the treatment of early-stage breast cancer, there is a lack of evidence regarding the safety of combining these agents with adjuvant RT, which typically involves moderate to high radiation doses." (PMID 40430137, 2025). "Indeed, in vitro kinase assays using purified components and 10 μM ATP showed that CRAF efficiently phosphorylates purified CDK4 at T172, whereas CDK7 and c-Jun N-terminal kinase (JNK) were excluded as relevant CAKs in the context of NF1-depleted ER+ breast cancer." (PMID 41226361, 2025). "The potential effectiveness of CDK4/6 inhibitors dalpiciclib in this study suggests they might potentially be an effective chemotherapy-free option for patients with ER-positive, HER2-positive breast cancer." (PMID 40743286, 2025). "Here, the authors identify that in breast cancer cells ZDHHC3-catalyzed B7-H4 palmitoylation prevents its lysosomal degradation and maintains immune suppression, which can be targeted by Abemaciclib to enhance lysosome activation independently of CDK4/6 inhibition." (PMID 40341398, 2025). "The SONIA study evaluated the efficacy of CDK4/6i added to either first- or second-line endocrine therapy in patients with hormone receptor-positive, human epidermal growth factor receptor 2 (HER2neu) receptor-negative breast cancer." (PMID 39954390, 2025). "Palbociclib, a cyclin-dependent kinase 4/6 (CDK4/6) inhibitor, combined with aromatase inhibitors (AI), can be used in first-line treatment for estrogen receptor (ER) positive, human epidermal growth factor receptor 2 (HER2) normal advanced breast cancer (ABC)." (PMID 40500959, 2025). "Combination with drugs that target CDK4/6, CYP17A1, or the PI3K/AKT/mTOR pathway, immunotherapies, or conventional treatments such as chemotherapy and radiotherapy may enhance the efficacy of breast cancer treatment." (PMID 39851328, 2025). "Particularly, a phase III trial (VIKTORIA-1, NCT05501886) is evaluating gedatolisib, an intravenously administered pan-PI3K/mTOR inhibitor, in combination with fulvestrant with or without palbociclib in advanced or metastatic HR+/HER2− breast cancer that is progressing on or after AI plus CDK4/6i." (PMID 40244377, 2025). "Notably, CDK4 overexpression was observed in 9.8% of the pretreated ER+/HER2− relapsed breast cancer patients, compared to just 1.5% in the untreated ER+/HER2− metastatic cohort (p = 2.82 × 10−4) and in all three early breast cancer cohorts." (PMID 40244377, 2025). "Although CDK4/6i has been clinically approved for breast cancer treatment, CDK4/6i monotherapy did not induce cytotoxicity in HL60 cells, as evidenced by the maintenance of their immature state and their rapid re-entry into the cell cycle after the drug was removed." (PMID 40753178, 2025).